SF1 (splicing factor 1)
Diseases named in the same sentence as SF1 in open-access papers (continued):
Sharing a sentence is not in itself a finding about the gene and the disease.
tumor (continued). "These tumours often express sex cord stromal tumour markers such as inhibin, calretinin and SF1." (PMID 41384702, 2026). "The tumor cells were diffusely positive for α-inhibin, SF1, FOXL2, WT1, and Vimentin." (PMID 41584573, 2025). "Specifically, in FOXL2+COL1A1− cells, we examined expression of other AGCT tumor markers such as SF1, calretinin, and inhibinα, whereas in FOXL2+COL1A1+ cells, we also examined expression of stromal markers, including αSMA, vimentin, S100A4, PDGFRa, PDGFRb, and FAP." (PMID 41042551, 2025). "Tumor cells were positive for α-inhibin, SF-1, FOXL2, WT-1, and Vimentin." (PMID 41584573, 2025). "Since 2017 (according with World Health Organization), they are divided into seven morphofunctional types and three lineages: somatotroph, lactotroph, and thyrotroph (PIT1 lineage), corticotroph (TPIT lineage) or gonadotroph (SF1 lineage), null cell or immunonegative tumor and plurihormonal tumors." (PMID 40643539, 2025). "Nonetheless, data from the current study suggest that SF1 gene expression is similar in the two groups of GnPT and that pSF1 tumors do not represent per se a distinct “high-risk” tumor phenotype." (PMID 38095839, 2024). "Subsequently, the same group reported another tumour co-expressing SF-1 and PIT-1, this time proposing that co-expression of multiple transcription factors may arise in a “poorly differentiated stem cell tumour”." (PMID 38483762, 2024). "Authors postulated that low SF-1 expression in gonadotroph tumours may represent intratumoural heterogeneity and lesser differentiation." (PMID 38483762, 2024). "SF1 immunofluorescence staining was performed to confirm the adrenal cortex origin of tumor cells." (PMID 38779454, 2024). "In order to further explore patient and tumor characteristics of DGST-PIT1/SF1, DGST-PIT1, and SGST-PIT1 across studies in a large meta-analysis, we integrated clinicopathological data of our in-house series and public deposits of five previously published studies." (PMID 38228887, 2024). "The first reported a tumour co-expressing SF-1 and PIT-1 and proposed that multiple cellular commitment transcription factors within one population may arise in context of a collision tumour." (PMID 38483762, 2024). "Tumor cells are usually positive for calretinin, SF1, smooth-muscle actin, and may express FOXL2, inhibin, and focally AE1/AE3, ER/PR, without nuclear expression of β-catenin or CyclinD1 positivity." (PMID 38136408, 2023). "Immunohistochemistry corresponds to typical sex cord-stromal tumour profile (positivity for SF1, calretinin, inhibin, vimentin, often FOXL2; often oestrogen and progesterone receptor expression; and negativity or weak patchy staining for keratin, negativity for EMA, PAX8, and PAX2)." (PMID 36399188, 2023). "In contrary to double tumors our tissue staining of somatotroph PitNETs of transcriptomic group 1 clearly showed the co-expression of PIT-1 and SF-1 over the entire tumor sample area, clearly indicating the homogenous nature of these double-positive somatotroph PitNETs." (PMID 36497102, 2022). "Our results showed a positive expression of SF-1 in all tumor samples." (PMID 35721701, 2022). "Analysis of FSH and SF1 expression of a gonadotroph tumour confirmed the feasibility of our technical approach, giving us the possibility to quantify and address the spatial distribution of immunoreactive cells in a large number (hundreds of thousands) of cells per section." (PMID 35139928, 2022). "Thus, congenitally lowered SF1 reduces tumor initiation in both the DND1Ter and ApcMin/+ mouse model systems of cancers that occur in young mice." (PMID 33202710, 2020). "Steroidogenic factor 1 (SF-1) is expressed in GT, and Pit1 is expressed in tumours derived from the production lines of growth hormone (GH) (somatotroph tumours, ST), prolactin (PRL) (lactotroph tumours, LT) and thyroid-stimulating hormone (TSH) (thyrotroph tumours, TT)." (PMID 29979686, 2018).
tumor (continued). "MUC-1 tumor analysis revealed highly vascularized, proliferating and SF-1 positive xenografts." (PMID 27764813, 2016). "In the future tumour grade, and other prognostic markers may be of value in the prognostic appraisal such as gene profiling, steroidogenic factor 1 (SF-1) or β-Catenin." (PMID 26984275, 2016). "Moreover, immunostaining against PIT1, TPIT and SF1 showed only sparse positive cells within the lesions, suggesting lack of commitment into endocrine precursors and supporting the undifferentiated nature of the tumour cells." (PMID 30912742, 2019). "To verify the observation that a distinct set of genes is regulated by SF-1 in double-positive somatotroph and gonadotroph PitNETs, we established regulons of NR5A1 in gonadotroph tumor cells and double-positive somatotroph tumor cell independently." (PMID 40813692, 2025). "Tumor cells from gonadotroph PitNETs closely resembled normal gonadotroph cells, whereas all tumor cells from somatotroph tumors — including the PIT-1/SF-1 double-positive tumors — clustered with normal PIT-1 lineage cells." (PMID 40813692, 2025). "These FOXL2+ cells in the COL1A1+ regions frequently co-stained with other tumor markers from our IMC panel, including SF1, calretinin, and inhibinα." (PMID 41042551, 2025). "Our panel included markers of tumor cells [FOXL2, ERα, PR, steroidogenic factor 1 (SF1), calretinin, and inhibin α (inhibinα)]." (PMID 41042551, 2025). "Compared to the previously established normal reference, the proportion of epithelial cells was significantly higher in PIT1, SF1, and TPIT lineage tumors, which suggested possible abnormal proliferation of tumor cells." (PMID 38167466, 2024). "The samples contained four major types of PitNETs according to clinical diagnosis: PIT1-lineage PitNET, SF1-lineage PitNET, TPIT-lineage PitNET, and null cell tumor (NCT)." (PMID 38167466, 2024). "In the single T-PIT lineage tumour, relative T-PIT mRNA expression was markedly elevated, PIT-1 was suppressed, and some SF-1 expression present." (PMID 38483762, 2024). "SF-1, GnRHR, LH, and FSH were positive in various proportions of cells within the tumor, whereas GH was positive in all cells throughout the tumor (Data not shown)." (PMID 38954291, 2024). "Integrated molecular analyses including publicly available samples confirmed that DGST-PIT1/SF1, DGST-PIT1 and SGST-PIT1 represent distinct tumor subtypes." (PMID 38228887, 2024). "Tumor cells are typically positive for sex cord–stromal markers (FOXL2, inhibin, calretinin, SF1, WT1, CD56)." (PMID 38136408, 2023). "Immunohistochemically, tumor cells are positive for CD10, cyclin D1 and vimentin and variably positive for WT1, FOXL2, and SF1." (PMID 36428715, 2022). "Immunohistochemical staining for SF-1, P450scc, CYP17A, CYP21A, and CYP11B1 indicated that this tumor produced cortisol." (PMID 35966069, 2022). "In cultures of ACA cells obtained from pediatric tumor fragments, ACA-T7 cells, TCF21 silencing by small interfering RNA led to an increase in SF1 mRNA expression." (PMID 33729392, 2021). "TCF21 binds directly in the E-box promoter sequence of steroidogenic factor 1 (SF1/NR5A1), decreasing SF-1 transcription in both the human ACC cell line (H295R) and in ACC cell culture obtained from patient tumor fragment (ACC-T36)." (PMID 33729392, 2021). "Pit-1 and SF-1 markers demonstrated comparable expression in pituispheres and FFPE of tumor tissue obtained from the same patient." (PMID 32528411, 2020). "The tumour was positive for adrenocorticotropic hormone, chromogranin A (CGA), and steroidogenic factor-1 (SF-1) on the tumour surface." (PMID 28193212, 2017). "In a next step, we analyzed SF-1 RNA and protein levels in all currently available ACC tumor models by quantitative real time PCR and immunohistochemistry, respectively." (PMID 27764813, 2016). "In a next step, we characterized all currently available human tumor models for ACC for Ki67, SF-1 and EGF-receptor status in comparison with MUC-1-xenografts." (PMID 27764813, 2016).
tumor (continued). "SF1 was also expressed in most AGCT tumor samples, though its staining seemed more diffuse than FOXL2; therefore, FOXL2 was used as the primary marker for tumor cell identification." (PMID 41042551, 2025). "Furthermore, our regulon analysis confirms a previous report that NKX2-2 transcription factor can be considered specific to PIT-1/SF-1 sPitNETs, as we observed the highest activity of NKX2-2 in this tumor subtype." (PMID 40813692, 2025). "Co-expression of SF-1 and PIT-1 has also been reported in two case reports, wherein authors suggested that such tumours may represent poorly differentiated stem cell tumours." (PMID 38483762, 2024). "In normal tissues: epithelial cells (stem-like cells and hormone-secreting cells), immune cells (T, B, lymphoid), stromal (fibroblast, endothelial).In tumor tissues: PIT1-lineage PitNET, SF1-lineage PitNET, TPIT-lineage PitNET, and null cell tumor, and two clusters of tumor-associated macrophages." (PMID 39114291, 2024). "The PIT1 lineage tumor cells were more involved in glycoprotein metabolic and biosynthetic processes; the TPIT lineage was involved in the transport and exocytosis of ions; and SF1 lineage was involved in gland development and synapse-related process." (PMID 38658971, 2024). "In SF-1 lineage tumours (n = 12), relative SF-1 mRNA expression was elevated, but not significantly, whereas both PIT-1 and T-PIT expression were significantly suppressed." (PMID 38483762, 2024). "Notably, CX3CR1+ macrophages enriched NR5A1+ tumor cells and INHBA-ACVR1B were locationalized closely in the spatial transcriptome of SF1 lineage tissue." (PMID 38658971, 2024). "The normal cell types included lactotroph cells, somatotroph cells, gonadotroph cells, pituitary stem cells, endothelial cells, fibroblasts, macrophages, and T lymphocytes.The PitNETs tissues: PIT1, TPIT and SF1 tumor cell lineages, TPIT+SF1 co-expressing tumor." (PMID 39114291, 2024). "SF-1 expression was also present in Pit-1 lineage tumours but not statistically significantly higher than normal pituitary." (PMID 38483762, 2024). "The 9 plurihormonal tumours WDLD were all strongly and diffusely positive for SF-1 and PIT-1." (PMID 38483762, 2024). "The hormone negative but SF1 positive gonadotroph tumours were more often TGFBR3L negative than tumours staining for LHβ alone or both FSHβ and LHβ." (PMID 36952069, 2023). "Tumor cells are typically positive for α-inhibin, calretinin, SF1, Melan-A, CD56 and CD99, and negative for EMA and occasional expression of other keratin markers." (PMID 37518334, 2023). "Subsequent real time PCR investigations for potential changes in Ki-67 or SF-1 gene expression levels in tumor spheroid versus the appropriate monolayer cultures, did not reveal significant differences." (PMID 35879289, 2022). "As per immunohistochemistry, the tumor cells were diffusely positive for SF-1 and Ki-67, partially positive for inhibin, and negative for CAM5.2, CK7, CK20, C-KIT, CD30, LCA, GATA-3, TTF-1, and PAX8." (PMID 36335378, 2022). "In contrast, the tumor cells were nonreactive for SF-1, inhibin alpha, desmin, HHF35, HMB45, Melan A, MITF, c-kit, DOG1, cytokeratin AE1/AE3, h-caldesmon, STAT6, CD68, MDM2, CDK4, c17, DHEAST, 3BHSD, CD31, Factor 8, and ERG." (PMID 34797454, 2021). "Tumor cells were nonreactive for SF-1, inhibin alpha, desmin, HHF35, HMB45, Melan A, MITF, c-kit, DOG1, cytokeratin AE1/AE3, h-caldesmon, STAT6, CD68, MDM2, CDK4, c17, DHEAST, 3BHSD, CD31, Factor 8, and ERG." (PMID 34797454, 2021). "The expression levels of TFs and hormones in the two “null cell tumors” appear to some extent inconsistent with IHC results, with one negative tumor showing relatively high expression levels of SF1/FSH and one with high expression levels of TPIT/ACTH." (PMID 34758873, 2021). "Furthermore, we found that TGFBR3L correlated with tumour FSH and LH staining, and 3-plex staining revealed an overlap of TGFBR3L positive cells, SF1, as well as FSH and LH positivity." (PMID 33396509, 2020).
tumor (continued). "(D) Immunofluorescence staining for lineage-committed progenitor markers PIT1, TPIT and SF1 shows the near absence of committed cells in tumours." (PMID 30912742, 2019). "RUNX, ZRSR2, and SF1 have also been reported in MDS; RUNX1 plays an important role in regulating the transcription of many tumor-suppressor genes, while ZRSR2 is an essential component of the splicing machinery, and SF1 is a component of the RNA-splicing machinery." (PMID 27959900, 2016). "In case 2, assessing the gene expression levels for SF-1 and CYP19A1 in the tumor by RT-qPCR showed that they were consistent with the results of immunohistochemical studies; both SF-1 and CYP19A1 genes were expressed in the tumor." (PMID 26576867, 2015). "The near absence of SF-1 expression suggests that infiltrating lymphocytes only make up a minor component of the tumour cell population in our samples." (PMID 26280373, 2015). "As SF-1 and WT1 are involved in the development of tumour, the FATE/BJ-HCC-2 may also be involved in tumourigenesis." (PMID 12865919, 2003). "None of the controls or male Sf1-Rspo1GOF animals displayed any malignant tumor; thus, sexual dimorphism might also characterize tumor progression, but analysis of more animals is required to draw this conclusion." (PMID 37102205, 2023). "These tumor-spheroids were furthermore SF-1 positive, but 3betaHSD negative (data not shown)." (PMID 35879289, 2022). "Immunohistochemically, the tumor cells were positive for epithelial markers (AE1/AE3, EMA), a smooth muscle marker (desmin), and less specific sex-cord markers (CD56, WT-1, CD99), but negative for relatively specific sex-cord markers (α-inhibin, calretinin, FOXL2, and SF1)." (PMID 32921307, 2020). "The location of human SF-1 in the region of 9q33 supports our hypothesis that SF-1 is a candidate tumor suppressor gene in the ovary and that abolished or aberrant SF-1 expression in OSE cells may promote tumor growth." (PMID 23291911, 2013). "We observed that SF-1 and P450scc are co-expressed in PA cells of MENX-affected animals, and both siRNA-mediated silencing of the Nr5a1 gene and treatment with the SF-1 inhibitor IsoQ resulted in the down-regulation of Cyp11a1 in rat primary tumor cells and in LβT2 gonadotroph cells." (PMID 23756599, 2013). "Interestingly, the regulatory network analysis revealed genes that may be indirect targets of SF-1, not just in tumor cells but also in other cell types in the ACC TME." (PMID 36835002, 2023). "Additionally, Cytokeratin 7 and 20, CD56, synaptophysin, chromogranin, SF1, α-inhibin, WT1, desmin, SMA, GATA3, Uroplakin II, CD10, PR, CD5, BerEP4, and NUT were negative in tumor cells, no loss of INI1 expression, β-catenin showed only membranous staining without nuclear accumulation (no shown)." (PMID 37518334, 2023). "A notable limitation is the inability to apply full WHO 2022 tumor classification, as transcription factor profiling (PIT1, TPIT, SF1) was not routinely available during the study period." (PMID 41480366, 2025). "None of the evaluated demographic (age, gender), clinical (tumor size, hormonal activity), or histopathological parameters (expression of transcription factors PIT-1, TPIT and SF1, P16) had a significant impact on the frequency of hrHPV DNA detection." (PMID 40002278, 2025). "Pathological examination confirmed double PitNETs comprising a GH/TSH secreting mature plurihormonal PIT1-lineage tumor (GH++, TSH±, PRL-, PIT1+) and a non-functioning gonadotroph tumor (FSH+, SF1+)." (PMID 40002269, 2025).
tumor (continued). "Based on the 2022 WHO classification, the majority of NF-PitNET was SF-1-lineage tumours (58.4%), followed by TPIT-lineage tumours (18.6%), tumours with no distinct lineage (16.8%) and Pit-1-lineage tumours (6.2%)." (PMID 38756997, 2024). "Tumor cells diffusely and intensely express WT1, FOXL2, and SF1, but are usually negative for EMA, AE1/AE3, inhibin, and calretinin." (PMID 38136408, 2023). "The major pituitary adenoma lineages are: PIT1 (lactotroph, somatotroph, and thyrotroph tumours), TPIT (corticotroph tumours), SF1 (gonadotroph tumours), and no distinct cell lineage (null-cell and plurihormonal tumours)." (PMID 38075079, 2023). "Some exceptional plurihormonal tumours from different lineages were also observed; two ACTH/LH ± α-subunit glycoprotein, two ACTH/GH ± PRL, one TSH/FSH/LH (SF-1, but not Pit-1 positive)." (PMID 36018781, 2022). "Strong co-expression of SF1 and PIT1 across a majority of tumour cells, illustrated in this study, excludes the possibility of entrapped normal cells." (PMID 36271964, 2022). "Fourteen NF tumours were immunonegative for all hormones tested, and 4/14 had additional transcription factor staining and tested negative for SF-1, Pit-1, and TPIT, thus classified as null-cell tumours." (PMID 36018781, 2022). "Tumor cells are usually negative for cytokeratin, epithelial membrane antigen, synaptophysin, chromogranin, INSM1, inhibin, calretinin, and SF1." (PMID 36428715, 2022). "Transcription factor IHC in the clinically non-functioning tumours was more varied, with 2 co-expressing PIT1 and SF1, 2 co-expressing TPIT and SF1 and 1 transcription factor negative." (PMID 36271964, 2022). "The ACSL1 encoded protein, involved in fatty acid metabolism, was positive in tumor cells from TPIT tumors and only very weak or negative in tumors of the PIT1 and SF1 lineage." (PMID 34758873, 2021). "The SF1 cluster contains four non-functioning TPIT tumors and one FSH-producing PIT1 positive tumor." (PMID 34758873, 2021). "TGFBR3L showed membranous immunolabeling and was found to be gonadotroph cell lineage-specific, verified by co-expression with SF1 and FSH/LH staining in both tumour and non-neoplastic anterior pituitary tissues." (PMID 33396509, 2020). "In our case, cabergoline might have promoted PA, which is consistent with the reported efficacy of cabergoline in inducing tumor shrinkage of non-functioning PitNETs that express D2Rs, including silent PIT1 and SF1 or NULL tumors." (PMID 40725781, 2025). "In our case, cabergoline might have promoted PA, which is consistent with the reported efficacy of cabergoline in inducing tumor shrinkage of non-functioning PitNETs that express dopamine 2 receptors, including silent PIT1 and SF1 or NULL tumors." (PMID 40725781, 2025). "To test whether Panobinostat may inhibit human PitNET growth, we cultured the primary tumor cells from 18 PitNET patients, including PIT1-lineage (n = 7), TPIT-lineage (n = 1), SF1-lineage (n = 8), No distinct cell lineage (n = 2)." (PMID 38637883, 2024). "However, tumor cells have an abnormalphysiology, so it has remained unclear whether POD-1 also controls SF-1 expression innormal, non-transformed adrenal cells." (PMID 26421867, 2015).